NSFP1 (N-ethylmaleimide-sensitive factor pseudogene 1)
Synonyms: formerly NSFP
Gene: Transcribed unprocessed pseudogene on chromosome 17 (46,372,855 to 46,487,141, forward strand). Ensembl gene ENSG00000260075.
Diseases named in the same sentence as NSFP1 in open-access papers:
NSFP1 is named in the same sentence as 2 diseases in open-access papers, as found by Europe PMC text mining. Sharing a sentence is not in itself a finding about the gene and the disease. The quoted sentences say what the papers report.
breast carcinoma (1 paper, 2023). "The same exon boundary of NSFP1 Exon 13 LRRC37A2 Exon 2 identified by the CLC Genomics workbench 20.0 (Qiagen) on the breast cancer dataset presented here was also found in the fusions uncovered TCGA and MDACC datasets." (PMID 37744342, 2023).
NSFP1 also shares sentences with these, for which no sentence is quoted: COVID-19 (1 paper).